MIR206 (microRNA 206)
Synonyms: hsa-mir-206; MIRN206; miRNA206; mir-206
Gene: MicroRNA gene on chromosome 6 (52,144,349 to 52,144,434, forward strand). Ensembl gene ENSG00000207604.
Pathways (Reactome):
Signal Transduction: Pre-NOTCH Transcription and Translation
Gene Ontology:
Biological process: miRNA-mediated post-transcriptional gene silencing
Cellular component: RISC complex
Homologues: Orthologues: chimpanzee ptr-mir-206 (100% identical), macaque mml-mir-206 (100% identical), pig ssc-mir-206 (85% identical), rat Mir206 (84% identical), guinea pig MIR206 (80% identical), rabbit MIR206 (79% identical), zebrafish mir206-2 (74% identical), tropical clawed frog xtr-mir-206 (73% identical), mouse Mir206 (71% identical), zebrafish mir206-1 (71% identical), dog MIR206 (67% identical), Caenorhabditis elegans cel-mir-1 (59% identical), and 1 more. Paralogues in human: MIR1-2 (71% identical), MIR1-1 (62% identical).
Diseases named in the same sentence as MIR206 in open-access papers:
MIR206 is named in the same sentence as 7 diseases in open-access papers, as found by Europe PMC text mining. Sharing a sentence is not in itself a finding about the gene and the disease. The quoted sentences say what the papers report.
bipolar disorder (1 paper, 2023). A disorder of the brain that causes unusual shifts in mood, energy, activity levels and the ability to carry out day-to-day tasks. "Additionally, MIR206 and the miR-133/206 cluster had several significant associations with similar neurodevelopmental and/or neuropsychiatric disorders (schizophrenia, bipolar disorder, and ASD)." (PMID 37679839, 2023).
muscular atrophy (1 paper, 2017). The loss of muscle tissue due to inactivity or disease. "However, after one year from symptoms onset, FGFBP1 and MIR206 levels decrease, which may cause the muscle to be less prone to react to denervation and muscular atrophy." (PMID 28842714, 2017).
tumor (3 papers, 2018 to 2025). "MiR206, as a tumor suppressor, regulated several oncogenes expression in various types of tumor cancers." (PMID 29391067, 2018). "In addition, MIR206, a key microRNA that regulates skeletal myogenesis and functions as a tumor suppressor in RMS34, was also found to be driven by a SE co-occupied by CASZ1, MYOD and MYOG." (PMID 32060262, 2020).
cancer (1 paper, 2023). A tumor composed of atypical neoplastic, often pleomorphic cells that invade other tissues. "In estrogen receptor-positive cancer with mass lesion type, CCL3L1 (21-fold), SNHG12 (11-fold), and MIR206 (sevenfold) were upregulated, and MIR597 (265-fold), MIR126 (12-fold), and SOX17 (fivefold) were downregulated." (PMID 37391754, 2023). "In ER-positive cancers, CCL3L1, SNHG12, and MIR206 were upregulated 21-fold, 11-fold, and sevenfold, respectively, in mass–type cancers, compared to non-mass enhancement–type cancers." (PMID 37391754, 2023).
MIR206 also shares sentences with these, for which no sentence is quoted: glioblastoma (1 paper); rhabdomyosarcoma (1); schizophrenia (1).